AVP (arginine vasopressin)
Diseases named in the same sentence as AVP in open-access papers (continued):
Sharing a sentence is not in itself a finding about the gene and the disease.
schizophrenia (23 papers, 2015 to 2025). A major psychotic disorder characterized by abnormalities in the perception or expression of reality. "The AVP gene is significantly associated with SZ and AVP protein levels are decreased in the plasma of male schizophrenia patients." (PMID 29108272, 2017). "Although the relationship between AVP and social behavior disorders has been difficult to establish in males, plasma levels of AVP have been linked to severity of psychosis in women with schizophrenia." (PMID 25705203, 2015). "Polymorphisms reducing AVP gene expression have been linked to schizophrenia." (PMID 33477721, 2021). "Previous research has highlighted the involvement of OXT/AVP pathways in psychotic disorders such as schizophrenia." (PMID 37373400, 2023). "OXT and AVPR1a gene expression at both the mRNA and protein levels were significantly lower in the schizophrenia group, and OXTR and AVP gene expression at both the mRNA and protein levels was higher in the schizophrenia subjects than in the controls." (PMID 35723404, 2022). "The expression of OXT, OXTR, AVP, and AVPR1a genes at the mRNA and protein levels differ between the studied groups of patients with schizophrenia and the control group." (PMID 35723404, 2022). "OXT and AVPR1a gene expression was significantly lower in the schizophrenia group than in the controls, whereas OXTR and AVP gene was significantly higher in the schizophrenia subjects than in the controls." (PMID 35723404, 2022). "The aim of this study was to evaluate the expression of OXT, OXTR, AVP, and AVPR1a genes at the mRNA and protein levels in patients with schizophrenia." (PMID 35723404, 2022). "The aim of this study was to evaluate the expression of OXT, OXTR, AVP, and AVPR1a genes at the mRNA and protein levels in patients who have been suffering from schizophrenia for a long or short time." (PMID 35723404, 2022). "Reduced AVP was found in patients with schizophrenia and bipolar disease, with lower AVP levels possibly predisposing to psychoses, independent of OT." (PMID 33477721, 2021). "There is a growing literature about OT and AVP in a range of disorders including schizophrenia, COMD, bipolar disorder as well as neurodevelopmental disorders." (PMID 27920663, 2016). "In contrast, phencyclidine (PCP) can induce severe symptoms of schizophrenia by elevating plasma AVP levels and by altering cerebral AVP receptor expression and distribution." (PMID 25853137, 2015). "The statistical analyses comparing the expression values of OXT, OXTR, AVP, and AVPR1a genes in the investigated groups allow us to conclude that all the examined genes may participate in the etiopathogenesis of schizophrenia." (PMID 35723404, 2022). "We might assume that reduced AVP signaling in the Brattleboro rats—through histone modification—may influence the dopaminergic system leading to development of schizophrenia-like symptoms." (PMID 34502322, 2021). "During acute schizophrenia, the plasma level of AVP is elevated." (PMID 25853137, 2015). "Interestingly, similar to work in animal studies, treatment of patients with memory deficits (e.g., with schizophrenia) with exogenous neuropeptides such as arginine vasopressin has been shown to have potential therapeutic benefits for cognitive and memory functions." (PMID 38254919, 2023). "OXT, OXTR, AVP, and AVPR1a are genes that may be involved in the development of schizophrenia." (PMID 35723404, 2022). "Our research group demonstrated the possible role of histone modification in the development of schizophrenia-like behavior in genetically AVP deficient Brattleboro rat (without changes in the enzymes responsible for DNA methylation, DNA methyltransferase, DNMT1 and DNMT3a)." (PMID 34502322, 2021). "This suggests that AVP may play a role in pathophysiology of schizophrenia." (PMID 25853137, 2015). "In this study, we examined the relative mRNA expression of OXT, OXTR, AVP, AVPR1a and CD38 in HC and first-episode, unmedicated schizophrenia (FES) patients." (PMID 29108272, 2017).
schizophrenia (continued). "Arginine vasopressin (AVP) has emerged as a candidate neuropeptide through which two such groups of disorders, autism spectrum disorders and schizophrenia, might impact social function." (PMID 27066536, 2016). "The blood AVP levels in patients with schizophrenia were either elevated or not altered." (PMID 35207180, 2022). "Moreover, the arginine vasopressin (AVP) system, which is evolutionarily related to the OXT system, shows cross-talk with the OXT system in a variety of different contexts, such as female aggression, substance use disorder, or ASD and schizophrenia." (PMID 34445168, 2021). "The lack of a significant difference in AVP gene expression between long- and short-term patients may suggest that the involvement of vasopressin in the etiopathogenesis of schizophrenia is a phenomenon that is occurring from the beginning of the illness and does not change with time." (PMID 35723404, 2022). "Arginine vasopressin (AVP) plays an important role in the development of several social and affective behaviors (reviewed in10,11), and some evidence suggests there may be a link between altered AVP function and neurodevelopmental disorders, including ASD, ADHD, and schizophrenia." (PMID 31160697, 2019).
Stroke (23 papers, 2010 to 2025). Sudden impairment of blood flow to a part of the brain due to occlusion or rupture of an artery to the brain. "Several studies indicate excess release of AVP in association with somatic and psychological stressors present in acute onset diseases, including myocardial infarction, sepsis, and stroke." (PMID 36768443, 2023). "We then discuss the underlying mechanisms contributing to AVP hypersecretion during the onset of the cerebrovascular accident and how this phenomenon causes detrimental effects on both systemic and local scales." (PMID 36768443, 2023). "Although there are many overlapping causes of low sodium levels in stroke patients, AVP’s role seems significant, especially in hemorrhagic stroke." (PMID 36768443, 2023). "A significant rise in blood AVP level is associated with an increase in the size of infarct core area and post-stroke edema." (PMID 37342100, 2023). "Population-based studies have shown copeptin to be strongly associated with microalbuminuria, suggesting a role for the AVP system in the development of albuminuria, which has been linked to incident stroke in diabetes as well as in the general population." (PMID 27312697, 2016). "Indeed, AVP hypersecretion is implicated in major stroke-related complications, including brain edema, vasoconstriction, oxidative stress, BBB disruption, and neuroinflammation." (PMID 36768443, 2023). "Moreover, an association between increased levels of AVP in stroke patients and poor prognosis has been established." (PMID 36768443, 2023). "However, AVP secretion also occurs during stress-related stimuli associated with acute onset diseases, including stroke, in a hypersecretion manner." (PMID 36768443, 2023). "For example, AVP-induced events (such as cerebral edema) are associated with stroke." (PMID 28865453, 2017). "AVP has an important role in the development of cerebral edema, which increases the severity of a stroke." (PMID 39777314, 2024). "As we highlight throughout the narrative, critical gaps in the literature exist and indicate the need for further research to understand better AVP mechanisms in stroke." (PMID 36768443, 2023). "AVP constitutes a key regulator of water balance within brain tissue and is being produced shortly following stroke in equimolar amounts to copeptin." (PMID 36648972, 2023). "As summarized above, increases in AVP are detrimental to stroke and have a considerable potential of being used as a therapeutic target as the mechanisms are directly associated with AVP receptors." (PMID 36768443, 2023). "The release of AVP, and other stroke-related events, such as cytokine release and ischemic disruption of HPA inhibitory areas, can entail the HPA axis activation." (PMID 36768443, 2023). "Being derived from pro-vasopressin along with AVP, copeptin reflects the activation of the endogenous stress system, exhibiting prognostic potential in stroke patients." (PMID 36648972, 2023). "Brain edema after stroke is closely related to arginine-vasopressin (AVP), a powerful endogenous hormone that regulates plasma osmolality and volume." (PMID 37342100, 2023). "In conclusion, overlapping detrimental events occurring both in stroke and AVP hypersecretion models and the effectiveness of AVP receptor antagonists provide evidence to infer that AVP plays a vital role in stroke development." (PMID 36768443, 2023). "After the stroke, elevated pools of circulating glutamate are detected in patients’ plasma and cerebrospinal fluid, which can directly interact with AVP neurons in PVN and SON." (PMID 36768443, 2023). "The discussion is primarily focused on AVP in ischemic stroke, as most data has studied this type of stroke." (PMID 36768443, 2023). "The ultimate goal of this review is to provide a springboard for further studies on the involvement of AVP in stroke settings and the implication thereof in modern medicine." (PMID 36768443, 2023).
Stroke (continued). "A mixed AVP antagonist, Conivaptan, achieved the best safety and neurological outcomes, providing the most significant degree of potential in stroke treatment." (PMID 36768443, 2023). "The multiplicity of mechanisms involved in primary and secondary brain damage in stroke points out the still underexplored areas of possible AVP influence." (PMID 36768443, 2023). "Following the hypersecretion of AVP during stroke onset, an early (1–2 h) increase of V1aR is observed in astrocytes, neurons during axonal beading, and brain endothelium." (PMID 36768443, 2023). "Still, monitoring AVP levels and using AVP receptor antagonists as an add-on therapeutic intervention are potential promises in clinical applications to alleviate stroke neurological consequences." (PMID 36768443, 2023). "In this review, we pointed out the involvement of AVP in some stroke-related pathophysiological events." (PMID 36768443, 2023). "During the acute phase of stroke, AVP release is uncontrolled and larger than observed in physiological conditions." (PMID 36768443, 2023). "Our goal is to provide the reader with a comprehensive, state-of-the-art narrative review highlighting AVP’s critical role in stroke pathology and its potential for therapeutic targets." (PMID 36768443, 2023). "The local mechanisms contributing to AVP release during stroke include glutamate release, local hyperosmotic environment formation, structural and functional changes in astrocytes located in PVN and SON, and pro-inflammatory mediators’ release." (PMID 36768443, 2023). "The release of AVP during stroke is also regulated by interactions of astrocytes and microglia with magnocellular neurons located in PVN and SON." (PMID 36768443, 2023). "In stroke, mechanical pressure created before/during edema formation exerts direct pressure on the hypothalamus, which results in AVP release from PVN and SON." (PMID 36768443, 2023). "The state of sympathetic predominance after stroke can cause catecholamines release, which activates the magnocellular neurons in PVN and SON, resulting in AVP release." (PMID 36768443, 2023). "During stroke, AVP is released from the posterior pituitary in response to histamine activation of magnocellular neurons in the hypothalamus AVP then interacts with its receptors V1a and V2 to mediate processes which lead to further cerebral edema." (PMID 25403760, 2014). "However, AVP acts synergistically with CRH and causes extensive ACTH release after stimulation by various acute stressors, including stroke." (PMID 36768443, 2023). "Thus, the significant influence of AVP on platelet aggregation in stroke is theoretically unlikely and unsubstantiated." (PMID 36768443, 2023). "AVP-mediated sympathetic activation and stroke-elicited disruption of central control of the autonomic nervous system could account for catecholamine release, and thus immunosuppression." (PMID 36768443, 2023). "Hence, copeptin has been used as a surrogate marker for AVP in multiple disease states, including myocardial infarction and stroke." (PMID 36768443, 2023). "All those functions are highly affected by a cerebrovascular accident, suggesting that dysregulated AVP release may play a significant role in stroke pathophysiology." (PMID 36768443, 2023). "Notably, AVP release in experimental stroke was found in the infarct and peri-infarct spatial location areas." (PMID 36768443, 2023). "Although the value of AVP level as a biomarker for predicting the outcome of stroke has yet to be established, experimental therapy using conivaptan, a mixed vasopressin antagonist, has been tested in stroke patients for brain edema management safely." (PMID 37342100, 2023). "However, the indirect nature of the gathered data does not provide us with the essential details to determine the overall involvement of AVP-mediated mechanisms in stroke." (PMID 36768443, 2023).
Stroke (continued). "We hypothesized that the reduction of lactate or BDNF expression by AVP might be related to the induction of stroke in the SHRSP/Izm rat strain." (PMID 28865453, 2017). "Future study may be required to evaluate effects of AVP and its receptor blocker conivaptan on stroke-triggered infarct volume in the brain." (PMID 28854286, 2017). "In particular, AVP influences astrocytic function, thereby contributing to the onset of stroke." (PMID 28865453, 2017). "Under ischemic conditions, AVP might be related to augmented inflammation and serine production, and perhaps stroke in SHRSP/Izm rats." (PMID 28865453, 2017). "Furthermore, left ventricular stroke work index was higher in the V2R-antagonist group than in the AVP group." (PMID 21054850, 2010). "The detrimental effects of AVP overproduction can be observed in patients with the syndrome of inappropriate antidiuretic hormone secretion (SIADH), which is commonly associated with stroke (3.9–45.3% and 40–45% on admission and during hospitalization, respectively)." (PMID 36768443, 2023). "Furthermore, under ischemic conditions, AVP might enhance inflammation and attenuate serine production as well as stroke in SHRSP/Izm rats." (PMID 28865453, 2017). "Future research will investigate copeptin in the diagnosis of AVP-dependent disorders of fluid homeostasis in infants and children as well, including nephrogenic and cerebral reasons such as increased intracerebral pressure after intraventricular hemorrhage, stroke, or traumatic brain injury." (PMID 27532032, 2016). "Clinical studies have shown that the plasma AVP level increases after ICH, stroke, and preeclampsia." (PMID 31949182, 2020). "Therefore, we designed a clinically relevant study to 1) investigate whether conivaptan can minimize brain edema and protect BBB after experimental stroke, and 2) to compare effects of two different AVP blockers conivaptan and tolvaptan on post-ischemic brain edema." (PMID 26275173, 2015). "Stroke is complicated by brain edema and blood-brain barrier (BBB) disruption, and is often accompanied by increased release of arginine-vasopressin (AVP)." (PMID 26275173, 2015). "During the acute phase of stroke, secretion of AVP occurs mainly from neurosecretory MNCs neurons located in the PVN and SON, as the AVP neurons are resilient to ischemia and are capable of secreting AVP after ischemic insult." (PMID 36768443, 2023). "The mechanisms for AVP release in stroke are independent of plasma osmolality and involve a complex interplay and synergism between regulatory systems, systemic factors, and local components." (PMID 36768443, 2023). "Another nonosmotic systemic stimulus contributing to AVP release during stroke is the increased intracranial pressure (ICP)." (PMID 36768443, 2023). "Arginine-vasopressin (AVP), a potent endogenous hormone responsible for regulating plasma osmolality and volume, has demonstrated a role in the pathophysiological mechanisms in stroke." (PMID 25403760, 2014). "Interestingly, in a previous study on stroke-heart syndrome, we found that a different Chinese medicine, Danhong injection, protected against ischemic stroke-induced cardiac dysfunction via the HPA-mediated adrenergic pathway in vivo or AVP signaling in vitro." (PMID 39479451, 2024). "It has been shown that cerebral ischemia may increase AVP levels in the plasma of patients with stroke and that V1R, but not V2R, is involved in the pathophysiology of secondary brain damage after focal cerebral ischemia." (PMID 35859595, 2022).
acute kidney injury (21 papers, 2009 to 2026). Sudden and sustained deterioration of the kidney function characterized by decreased glomerular filtration rate, increased serum creatinine or oliguria. "Notably, a post hoc analysis of the VASST data demonstrated a reduced rate of progression to acute renal failure in patients at risk for acute renal failure ('R', according to the RIFLE criteria) treated with AVP." (PMID 19664253, 2009). "Acute Kidney Injury (AKI) sub-phenotypes could be used to identify responsiveness to AVP in septic shock." (PMID 30736368, 2019). "A second sequela of asphyxia is the syndrome of inappropriate ADH secretion (SIADH), which is also a consequence of exceedingly high levels of AVP/ADH, renal failure, or both." (PMID 27532032, 2016).
pneumonia (21 papers, 2013 to 2025). An acute, acute and chronic, or chronic inflammation focally or diffusely affecting the lung parenchyma, caused by an infection in one or both of the lungs (by bacteria, viruses, fungi, or mycoplasma.). "This discrepancy may have been associated with more patients with pneumonia in the AVP group, which may have facilitated AVP secretion by hypoxemia, and could have an effect on our results." (PMID 29784057, 2018). "Pneumonia is a known cause of inappropriate antidiuresis syndrome (SIAD), which may have facilitated both baseline and osmoreceptor-mediated AVP secretion." (PMID 24223220, 2013).